MTOR (mechanistic target of rapamycin kinase)
Diseases named in the same sentence as MTOR in open-access papers (continued):
Sharing a sentence is not in itself a finding about the gene and the disease.
melanoma (continued). "Altogether, our work elucidated that downregulation of SPI1 hampered cell proliferation, metastasis and glycolysis in melanoma cells by blocking the AKT1/mTOR axis by targeting HK2." (PMID 37539493, 2023). "Further research showed that palbociclib induces senescence of melanoma cells by inhibiting mammalian target of rapamycin (mTOR) signaling." (PMID 37771436, 2023). "Research has shown that resveratrol can effectively reduce the activity of AKT/ERK, PI3K, mTOR and other signaling pathways, promote autophagy in melanoma cells, and inhibit the migration and invasion of melanoma cells." (PMID 38005336, 2023). "Baicalein and baicalin exhibited antitumor effects on melanoma cells due to inhibiting tumor cell glucose consumption and metabolism through the mTOR-HIF-1α signaling pathway." (PMID 36829966, 2023). "Moreover, the increase in HIF-1α induced by BRAF (V600E) mutation might significantly contribute to melanoma genesis in association with the PI3K/AKT/mTOR pathway, which is known to play a relevant role in early melanoma as well as resistance to BRAFi/MEKi therapy." (PMID 37895015, 2023). "Treatment of melanoma cells with single inhibitors of PI3K and mTOR caused a decrease in proliferation compared to control cells, an effect that was the most pronounced for the Mel-1359 cell line." (PMID 37097377, 2023). "That these include components of the Akt/mTOR signaling pathway (Akt S437, TOR S2448, PRAS40 T246) is not surprising since riluzole has been shown to inhibit Akt phosphorylation and synergize with mTOR inhibition in melanoma and glioblastoma models." (PMID 37766843, 2023). "Prior studies in melanoma and glioblastoma have shown that riluzole inhibits Akt phosphorylation and that riluzole combined with mTOR inhibition can synergistically decrease xenograft growth." (PMID 37766843, 2023). "PURPL physically interacts with ULK1 and differentially regulates its phosphorylation by promoting the association with mTOR and departure from AMPK to suppress autophagic cell death for maintaining the survivability of melanoma cells." (PMID 36918934, 2023). "Herein, we verified that SPI1 regulated HK2 expression, thereby mediating the AKT1/mTOR signalling pathway and promoting melanoma cell proliferation, metastasis and glycolysis." (PMID 37539493, 2023). "Our data suggest that the mechanism of action of p38–induced tumor suppressive effects in NRAS-mutant melanoma is through the activation of mTOR pathway, which in turn leads to suppressed autophagy and changes the dynamics of actin cytoskeleton." (PMID 36765834, 2023). "In an earlier study, authors report subcellular localization of Polκ inside nucleus of human melanoma cells and this involves mTOR pathway." (PMID 37697436, 2023). "It is noteworthy that the pathways identified through the FCS analysis supported the outcomes of the ORA analysis by enriching genes within melanoma, mTOR signaling, cell cycle, and MAPK signaling pathways." (PMID 37829282, 2023). "We aimed to study for the first time the anti-tumor activity of GP-2250 in BRAF-mutated melanoma cell lines and benign melanocytes, also addressing the expression of parts of the PI3K/AKT/mTOR signaling pathway." (PMID 37895015, 2023). "The p‐AKT1, AKT1, p‐mTOR and mTOR protein levels in melanoma tissues were detected by immunohistochemistry assay, indicating that p‐AKT1 and p‐mTOR proteins were significantly increased in melanoma tissues." (PMID 37539493, 2023). "Exogenous hydrogen sulfide restrains human skin melanoma development by facilitating autophagy in melanoma cells via the repression of the PI3K/AKT/ mTOR pathway." (PMID 36272879, 2023).
melanoma (continued). "Enhancement of oxidative stress repressed the PI3K/AKT/mTOR axis in melanoma cells via disturbance of downstream protein phosphorylation." (PMID 37539493, 2023). "Inactivation of PTEN in human cancer results in upregulation of the AKT pathway (mainly AKT3 in melanoma) and its substrate mTOR, therefore mediating tumorigenesis." (PMID 35621644, 2022). "The results indicated that phosphorylation of AKT and mTOR were decreased in melanoma cells after knockdown of Piezo1." (PMID 36112948, 2022). "For example, anti-PD-L1 antibodies downregulated Akt/mTOR pathway, significantly inhibiting the glycolysis of melanoma and correcting glucose restriction induced by tumors." (PMID 36620597, 2022). "In direct correlation, human melanomas with reduced IFN-γ signaling or ICB resistance exhibit upregulation of target genes in the mTOR and JAK1/2 pathways, indicative of their activation." (PMID 36008408, 2022). "The suppression of baicalein on melanoma cells through the inhibition of tumor cell glucose uptake and metabolism via affecting the mTOR-HIF-1α signaling pathway." (PMID 36432119, 2022). "Another study using melanoma cells found that resveratrol inhibits the survival and migration of melanoma cells via blocking the AKT/mTOR pathway, resulting in autophagy activation." (PMID 35566016, 2022). "The activation of the mTOR pathway can be inhibited by rapamycin; in turn, the treatment of melanoma cells with rapamycin decreases the surviving tumor-cell fraction." (PMID 36077992, 2022). "To establish the clinical relevance of our findings, we rationalized that IFNGR1Low SKCMs with impaired IFN-γ signaling and patient melanomas resistant to ICBs would house activated mTOR and JAK1/2 to some extent." (PMID 36008408, 2022). "In this context, fibroblasts were shown to be able to switch the phenotype of melanoma cells to the mesenchymal state by shifting the signaling to the PI3K/mTOR pathway in a fibronectin-dependent manner." (PMID 35214043, 2022). "We found that the Akt/PI3K/mTOR signaling pathway was activated in resistant melanoma cells, and then PCK1 was upregulated in also promoted cell proliferation, migration, and tumor stemness." (PMID 36700470, 2022). "In the following paragraphs, we provide an overview of metabolic adaptation mechanisms linked with drug resistance in melanoma, often associated with emerging alteration of nicotinamide adenine dinucleotide (NAD) metabolism and mTOR signaling." (PMID 36077374, 2022). "Studies have shown that in invasive metastatic melanomas, Akt serves as a molecular switch leading to upregulation of mTOR and of the downstream target, S6K1." (PMID 35163615, 2022). "A specific mTOR inhibitor, temsirolimus, exhibits synergistic action with hydroxychloroquine, an autophagy inhibitor, leading to cell death via apoptosis in melanoma cells." (PMID 35163615, 2022). "Another major player in this context is the mammalian target of rapamycin (mTOR) pathway, which plays key roles in the regulation of melanoma cell anabolic functions and energy metabolism at the switch between sensitivity and resistance to targeted therapy." (PMID 36077374, 2022). "Previously, PYCR1 knockdown has been shown to reduce p-mTOR in renal cell carcinoma and p70 in melanoma." (PMID 35105345, 2022). "mTOR inhibition can also enhance the maintenance and self-renewal of various stem cell types, and the relapse of advanced melanomas is believed to rely, at least in part, on “dormant” de-differentiated cancer cells with stem cell-like features." (PMID 36077374, 2022). "Reduced transport of glutamine and leucine by inhibition of ASCT2 in melanoma cells leads to decreased mTOR signaling, resulting in cell cycle arrest." (PMID 35565278, 2022). "A recent report has suggested that targeting mTOR signaling overcame acquired resistance in BRAF-mutant melanoma, implying targeting signaling pathways bypass MAPK/MEK signaling to bring out great improvement." (PMID 36034784, 2022).
melanoma (continued). "PTEN, which inhibits the PI3K/AKT/mTOR growth-promoting signaling cascade, is found in 38% of primary melanoma patients and 58% of metastatic disease patients." (PMID 36686734, 2022). "For example, incubation of keratinocytes with EVs derived from metastatic melanoma cells activates the AKT/mammalian target of rapamycin (mTOR) and extracellular-signal-regulated kinase (ERK) signaling pathways, thereby increasing cell migration ability." (PMID 35735488, 2022). "A concomitant loss of PTEN activates the PI3K/Akt/mTOR signaling, overcomes OIS induced by MAPK signaling, and results in melanoma formation with 100% penetrance." (PMID 36077374, 2022). "In BRAF mutated melanoma cell lines, the MEK/ERK pathway promotes the constitutive activation of mTOR through the p90 ribosomal S6 kinase RSK, inhibition of which abrogates tumor growth in mouse models." (PMID 35912100, 2022). "Of note, others have shown that CDKN2A deletion activates mTOR in melanoma tumors and induces S6 phosphorylation." (PMID 35385746, 2022). "High-glycolysis melanoma cells upregulates TGFB1 expression thus increasing the secretion of TGF-β which inhibit mTOR signaling pathway and result in less production of IFN-γ and impaired anti-tumor function." (PMID 36003368, 2022). "Taken together, according to the integration of metabolome and transcriptome analysis, we found that the mTOR pathway was significantly downregulated by NCTD in Vem-resistant melanoma cells, and validated these results by detecting the protein expression." (PMID 36034784, 2022). "Another suggested pathway for rewiring the resistance and the aggressiveness of melanoma is suppressing both mTOR and autophagy." (PMID 35163615, 2022). "The presence of mutations that render mTOR kinase refractory to inhibition by Rapalogs or mTOR kinase inhibitors is another potential mechanism of the resistance of melanoma cells to mTOR inhibition, although this represents a relatively rare event." (PMID 36077374, 2022). "The idea that mTOR activation plays essential roles in melanomagenesis is also strongly supported by work on murine melanoma models." (PMID 36077374, 2022). "Remarkably, we observed that PI3K/AKT/mTOR signaling sustained stem cell features from melanoma cells, as suggested by the abrogation of the SP by the dual PI3K/mTOR inhibitor dactolisib." (PMID 36434616, 2022). "It was found that coexpression of TAARs with genes inquired in neurotransmitter signaling is lost in melanoma, and tumor-specific association of TAAR6 expression with the mTOR pathway and inflammatory signaling is observed." (PMID 35053262, 2022). "According to previous sequencing studies, genetic aberrations in CDK and PI3K/AKT/mTOR pathways are frequently detected in acral and mucosal melanoma subtypes." (PMID 35596181, 2022). "Kaempferol suppressed cell migration and apoptosis in the presence of melanoma malignancy, as well as downregulating the levels of mTOR, phosphorylated (p) mTOR, PI3K, and Akt proteins." (PMID 35986346, 2022). "In summary, we investigated the oncogenic role of Piezo1 in melanoma and demonstrated the mechanism which Piezo1 regulated malignant progression of melanoma through the PI3K/AKT/mTOR signaling pathway." (PMID 36112948, 2022). "Mechanistically, we found that Piezo1 activated AKT/mTOR signaling to maintain malignant phenotypes of melanoma." (PMID 36112948, 2022). "Excess AKT/mTOR pathway activation had been identified as a facilitator of melanoma cell survival in the context of BRAFV600E inhibition." (PMID 35141161, 2022). "Dormant melanoma cells are characterized by low mTOR activity, and, in turn, mTOR inhibition is sufficient to promote cell cycle pausing and dormancy." (PMID 36077374, 2022). "Inactivation of Nav 1.6 by its inhibitor tetrodotoxin suppresses aggressive properties and promotes apoptosis in melanoma cells by reducing mTOR activity and interrupting the translocation of mitochondrial Ca2+ flux." (PMID 35162934, 2022).
melanoma (continued). "For EMT-related pathways, the modulations of ERK/AKT/mTOR in B16F1 melanoma cells and Wnt/β-catenin signaling in osteosarcoma cell lines (MG63, 143B) were reported." (PMID 36012338, 2022). "Exposure to rapamycin has been shown to decrease both the active form of mTOR and its active downstream protein p70-s6 kinase (p70S6K), resulting in decreased surviving fraction of canine melanoma cell lines in vitro." (PMID 34895222, 2021). "Similar to our findings, the PI3K/AKT/mTOR pathway was found to be active in canine melanoma and rapamycin halted the kinase cascade." (PMID 34895222, 2021). "Since both rapamycin and carboplatin have demonstrated activity in canine melanoma cells and patients, respectively, as single agents, the goal of this study was to evaluate the combined effect of mTOR small molecule inhibitors with carboplatin." (PMID 34895222, 2021). "The mTOR inhibitors were chosen as they interfere with the PI3K/AKT/mTOR pathway, a major proliferation cascade of relevance to canine melanoma." (PMID 34895222, 2021). "In our series, the co-occurrence of malignant melanoma and RCC was associated with germline variation in the PI3K/mTOR signaling cascade, with potential relevance for early diagnostic and clinical management." (PMID 34067022, 2021). "The activation of intrinsic signaling pathways (like MAPK or PI3K/Akt/mTOR) drives the utilization of the Warburg phenotype in melanoma cells." (PMID 33730175, 2021). "Established increased risk of renal cancer and/or melanoma is observed with BAP1 mutations responsible for BAP1-TPDS, PTEN-AKT1/2-PIK3CA induced PTEN-opathies, as well as mTOR signaling syndromes such as TSC1/2 tuberous sclerosis complex." (PMID 34067022, 2021). "Another study demonstrated that CR induced autophagy and inhibited proliferation and invasion of A375 and C8161 human melanoma cells by downregulating AKT/mTOR signaling pathway." (PMID 33467015, 2021). "PI3K/mTOR pathway activation has been associated with resistance to ICB in several cancer histotypes, including melanoma, prostate cancer, head and neck squamous cell carcinoma, and uLMS." (PMID 33922556, 2021). "In conclusion, rapamycin and everolimus successfully targeted the mTOR pathway in canine melanoma cells and decreased their glycolytic rate." (PMID 34895222, 2021). "As a result, the evaluation of glycolysis is relevant in canine melanoma cells which are known to have an active PI3K/AKT/mTOR signaling pathway." (PMID 34895222, 2021). "The protein kinase B (AKT)/mechanistic target of rapamycin (mTOR) signaling pathway was shown to be up-regulated in DTIC-treated T24.6.9 melanoma cells." (PMID 34926249, 2021). "Previous studies suggested that co-targeting the AKT/mTOR pathway reversed the resistance of some melanoma cell lines with intrinsic cross-resistance to BRAF and MEK inhibitors." (PMID 34304249, 2021). "Another study, focusing its attention on curcumin, demonstrated that the AKT/mTOR signaling pathway was downregulated, inducing autophagy in the case of A375 and C8161 human melanoma." (PMID 34575899, 2021). "PD-1 and PD-L1 are expressed not only on immune cells but also by some tumor cells, and PD-1 expression on melanoma cells was found to activate the mTOR signaling pathway." (PMID 34943938, 2021). "Sirolimus is a specific mTOR inhibitor and it was reported to induce the durable cytostatic effects in melanoma." (PMID 34987517, 2021). "The aim of this study was to evaluate the activity of the PI3K/AKT/mTOR pathway in four melanoma cell lines after being co-treated with carboplatin and one of two different mTOR inhibitors." (PMID 34895222, 2021). "Numerous in vitro studies indicated that resveratrol is able to induce autophagy, inhibiting the Akt/mTOR pathway in B16 melanoma cells." (PMID 34575899, 2021).
melanoma (continued). "The secretion of MDK by melanoma cells affects the expression of VEGFR3 on lymphatic endothelial cells through the paracrine effect of the mTOR pathway." (PMID 34759262, 2021). "By interacting with its cognate ligand, melanoma-PD-1 triggers the activation of downstream effectors (eg, ribosomal protein S6) of mTOR signaling, which further accelerate tumor growth." (PMID 33593825, 2021). "Among the 14 tested drugs, each at their MTD, only the rapamycin family of mTOR inhibitors (rapalogs) showed selective activity against nf1/pten-mutant melanoma in vivo as single agents." (PMID 34331013, 2021). "Our results indicate a high degree of diversity in the way the PI3K pathway is activated in different melanomas and that mTOR is the most effective point for targeting the growth via the PI3K pathway across all of these cells." (PMID 33549048, 2021). "For example, RSV triggered protective autophagy rough the ceramide accumulation and inhibition of Akt/mTOR pathway in B16 melanoma cells." (PMID 33467015, 2021). "Overall, this indicates a high degree of diversity in the way the PI3K pathway is activated in different melanoma cell lines and that mTOR is the most effective point for targeting the growth via the PI3K pathway across all of these cell lines." (PMID 33549048, 2021). "Our data suggest that Salmonella directly inhibited melanoma metastasis in both in vitro and in vivo models by suppressing the Akt/mTOR/SNAI1 signaling cascade." (PMID 34207850, 2021). "One of the pathways shown to be aberrantly activated in both human and canine melanoma is the phosphoinositide 3-kinase/protein kinase B/mechanistic target of rapamycin (PI3K/AKT/mTOR) signalling cascade." (PMID 34895222, 2021). "Previous studies have demonstrated that resistant melanoma cells displayed activated ERK due to a MEK2 mutation and BRAF amplification, which contributed to sustained mTOR activity in resistant cells." (PMID 34304249, 2021). "mTOR deregulation has been observed in many cancer types, including melanoma, and its inhibition has been investigated in clinical treatment." (PMID 33937086, 2021). "In our series, the PI3K/mTOR axis was targeted in sporadic cases as well as in cases with a positive family history of melanoma." (PMID 34067022, 2021). "The PI3K/AKT/mechanistic target of rapamycin (mTOR) pathway is another crucial pathway in melanoma development." (PMID 33692796, 2021). "Fisetin has inhibitory effects on the PI3K/AKT/mTOR pathway and demonstrated efficiency at inhibiting multiple cancers and specifically melanoma." (PMID 34066966, 2021). "As deregulation of the PI3K/AKT/mTOR signalling pathway is a major component of melanoma malignancy, much interest has been focused on its modulation in human cutaneous melanoma." (PMID 34895222, 2021). "Qualitative protein detection using western blot showed activation of the PI3K/AKT/mTOR pathway in the four canine melanoma cell lines evaluated in this study." (PMID 34895222, 2021). "Previous studies have examined the role of mTOR signaling in naive melanoma cell lines with de novo resistance or acquired resistance to BRAFi or MEKi." (PMID 34304249, 2021). "Since the PTEN can regulate the AKT activation, the PTEN mutation, observed in 10–30% of melanoma cell lines, can lead to stimulation of the PI3K/AKT/mTOR pathway." (PMID 33692796, 2021). "Another report showed that curcumin caused cell cycle arrest at the G2/M phase, and induced autophagy by downregulating Akt/mTOR axis in human melanoma A375 and C8161 cell lines." (PMID 34680593, 2021). "To date, there are no reports of clinical trials of pure mTOR kinase domain inhibitors in melanoma, although in phase-1 trials of dual PI3K/mTOR inhibitors showed some clinical activity against melanoma." (PMID 33549048, 2021). "Both mTOR inhibitors decreased the extracellular acidification rate of canine melanoma cells, indicating reduced cancer cell glycolytic activity." (PMID 34895222, 2021).